INS (insulin)
Diseases named in the same sentence as INS in open-access papers (continued):
Sharing a sentence is not in itself a finding about the gene and the disease.
Obesity (continued). "Adiponectin is a hormone that is primarily secreted by adipose tissue; it is inversely correlated with plasma insulin and is reduced in individuals with insulin-resistant conditions such as obesity and type 2 DM." (PMID 26222906, 2015). "In line with our previous work in rats, the findings of this study include significant effects of maternal obesity to increase body weight, fat and muscle mass, blood glucose, insulin and triglycerides in the offspring at PND19." (PMID 25853572, 2015). "Another relevant study displayed that fucoxanthin down-regulates stearoyl-coenzyme A desaturase-1 (SCD1), with subsequent improvement of insulin and leptin sensitivity, thus contributing to the prevention of obesity." (PMID 25871295, 2015). "In conclusion, we show for the first time that human oWAT fibrosis in severe obesity is consistent with a higher degree of insulin resistance measured by glucose clamp." (PMID 26258766, 2015). "HFD-stimulated sphingolipid generation contributes to systemic insulin resistance, dysregulated lipid accumulation, and cytokine expression and secretion from skeletal muscle and adipose tissues, exacerbating obesity-related conditions." (PMID 26648664, 2015). "Maternal obesity has been widely studied in rodent models where a maternal cafeteria or high fat (HF) diet during pregnancy has been shown to induce obesity, and insulin and leptin resistance in offspring." (PMID 25853572, 2015). "A study of genetically obese mice (ob/ob) and high-fat diet-induced obese mice found inhibiting ceramide de novo synthesis attenuated obesity symptoms, facilitating weight reduction, better energy metabolism, and improved insulin sensitivity." (PMID 25906159, 2015). "CD8+ cells accumulate into VAT in murine obesity and their depletion led to reduction of macrophage infiltration and amelioration of insulin sensitivity." (PMID 25759691, 2015). "To account for the impact of overall obesity on central adiposity and insulin sensitivity, we considered WHR and FI after adjustment for BMI (denoted WHRadjBMI and FIadjBMI, respectively)." (PMID 26132169, 2015). "These authors have shown that obesity-prone pup cross-fostered to obesity-resistant dams remained obese but improved their insulin sensitivity in adult life." (PMID 25926796, 2015). "Obesity has profound effects on tissue insulin sensitivity, and therefore on systemic glucose homeostasis." (PMID 25688211, 2015). "When administered to strain A×B19 by gavage, the dietary response was significantly blunted for obesity, plasma lipids, and insulin resistance." (PMID 26260972, 2015). "The ability of MnTBAP to enhance insulin action in mice with pre-existing diet-induced obesity in our studies is consistent with prior work indicating that MnTBAP improves insulin action in genetically obese ob/ob mice." (PMID 26397111, 2015). "One potential mechanism is that the inhibition of intestinal FXR signaling improves obesity and insulin responsiveness in HFD-fed mice." (PMID 26604978, 2015). "Loss of autophagy with haploinsufficiency of an essential Atg7 gene in murine models of obesity can lead to increased insulin resistance with elevated lipids and inflammation." (PMID 26064426, 2015). "A major limitation was the lack of patient information on body size that would permit evaluation of the relationship of insulin-axis protein expression by obesity status." (PMID 25619494, 2015). "Anserine and creatine are known to alter insulin secretion and glycogen metabolism, changes that ameliorate the obesity phenotype in a rodent model of obesity and in human clinical trials." (PMID 26052340, 2015). "Chen and colleagues showed that these DGAT1-deficient mice have decreased levels of skeletal muscle TAG after induction of high-fat-diet-induced obesity, in addition to increased sensitivity to insulin and leptin." (PMID 26942223, 2015).
Obesity (continued). "Together, these data indicate that activation of metabolic sensors in immune cells during obesity is essential for inflammation and insulin resistance development." (PMID 26779183, 2015). "Studies showed that physical activity can reduce the resting levels of these cytokines by reducing obesity, leptin and increasing the adiponectin and insulin sensitivity." (PMID 26687477, 2015). "The disturbances in the brain 5-HT signaling also result in eating disorders, metabolic dysfunctions and the decrease of insulin sensitivity, and can be a trigger for obesity, MS and T2DM." (PMID 28031898, 2015). "A recent study also identified TLR4 signaling pathway as a direct key mediator of vascular inflammation and impairment of endothelial insulin signaling in the setting of obesity." (PMID 25873766, 2015). "The focus of this study was insulin clearance, a key determinant of fasting and postprandial plasma insulin levels, which is known to be reduced in obesity particularly when features of the metabolic syndrome are present." (PMID 26297500, 2015). "The American Dietetic Association acknowledges that the consumption of viscous dietary fibre lowers blood cholesterol levels and helps to normalise blood glucose and insulin levels and therefore, is ideal for the treatment and prevention of obesity." (PMID 26825059, 2015). "In obese rats, the neutralization of TNF resulted in increased peripheral glucose uptake induced by insulin, and mice with a TNF gene deletion have significant improvement in their insulin sensitivity in both monogenetic and diet-induced obesity models." (PMID 25918733, 2015). "We recently identified a novel function for bilirubin as an insulin sensitizer that reduces obesity and hyperglycemia in obese mouse models." (PMID 26017184, 2015). "In rodent models of obesity, the normal hormonal response to the periparturient period is altered, with a lower rise in prolactin and insulin levels during the transition from pregnancy to lactation and significantly higher corticosterone levels." (PMID 25988133, 2015). "In animals, chronic intake of a high-fat diet (HFD) causes diet-induced obesity (DIO), which results in leptin and insulin resistance in hypothalamic neurons." (PMID 25786112, 2015). "Because IR is an essential event towards metabolic dysregulation in obesity, we tested the levels of glucose and insulin tolerance following pHBSP treatment in DIO mice." (PMID 26459940, 2015). "This review will examine how dysregulation of the insulin/IGF system, which occurs with obesity and metabolic syndrome, promotes cancer risk and progression." (PMID 26029167, 2015). "We also found that lipid, obesity-inflammation, and insulin sensitivity domains predominantly exist in the data of obese children." (PMID 26011530, 2015). "Numerous studies have reported the biological mechanisms linking obesity to cancer, including: insulin and insulin-like growth factor, sex steroids, adipokines, inflammation, and obesity-induced hypoxia." (PMID 25912035, 2015). "In obesity, Glut4 expression is decreased in adipose tissue and adipose-selective deletion of the Glut4 gene impairs insulin action in muscle and liver." (PMID 25774202, 2015). "The role of insulin in the pathogenesis of cancer has been increasingly emphasized because of the high incidence of obesity and metabolic syndrome and their correlated complication including cancer." (PMID 26084465, 2015). "Since TNBC lacks expression of hormone receptors, distinct molecular mechanisms must link obesity to this subtype of breast cancer, for example insulin resistance, secretion of pro-angiogenic adipokines such as leptin, and chronic inflammation." (PMID 26684197, 2015). "Our data demonstrate that insulin-induced microvascular recruitment is a significant mediator in the relationship between obesity and metabolic insulin sensitivity." (PMID 26003324, 2015).
Obesity (continued). "We have previously demonstrated the relationship between kinins and metabolic processes such as insulin and glucose homeostasis and obesity." (PMID 26302153, 2015). "Obesity increases intramyocellular TG in skeletal muscle, which impairs insulin sensitivity and decreases muscle strength." (PMID 26175963, 2015). "The HFHSD group pigs displayed obesity, high levels of insulin and dyslipidemia following consumption of the HFHS diet for 23 months." (PMID 26161779, 2015). "Animal models with ad libitum feeding of 40–60% high-fat (HF) diets successfully develop obesity, intrahepatic fat deposition, insulin resistance, and metabolic parameters resembling human NASH." (PMID 26090514, 2015). "The fcHFHS diet represents several features of the human obesity situation including increased fat mass, insulin resistance and peripheral leptin resistance compared to rats on the CHOW, fcHF, and fcHF diet." (PMID 26733840, 2015). "Extensive work has been done using various diet-induced obesity models to demonstrate an important role of hypoxia-induced signaling in adipose tissue and its impact on adipose functions related to adipogenesis, insulin sensitivity, and inflammation." (PMID 25852648, 2015). "Obesity measured by BMI, explains only one-third of the total variation in insulin sensitivity, which is more strongly correlated with central obesity and with the development of T2DM." (PMID 26489845, 2015). "In the in vivo proof of study principle, mice treated with peptides 10, 34, 49 and 51 were protected against high-fat diet-induced obesity and insulin resistant." (PMID 26296084, 2015). "AT is important during the insurgence of insulin resistance in the frame of obesity and produce factors involved in energy metabolism, such as chemokines/cytokines, and the pancreas is implicated in insulin production." (PMID 26337083, 2015). "Offspring of rat dams exposed to a chronic jet-lag paradigm from the first day of pregnancy to lactation day 10 developed metabolic problems such as obesity, hyperleptinemia, and glucose tolerance/insulin insensitivity when they reached maturity." (PMID 25988133, 2015). "We have also shown that insulin production, via effects on basal circulating insulin, is a key determinant of diet-induced obesity." (PMID 27019722, 2015). "Regarding to possible mechanism, it is suggested that increased circulating irisin in obesity is an adaptive compensatory response to obesity-induced disturbed metabolism such as decreased insulin level." (PMID 27354972, 2015). "This study was designed to unravel the role of adipocytes behind the link between obesity and insulin regulation in human." (PMID 25743104, 2015). "Although IR occurs in obese as well as lean subjects with PCOS, any degree of obesity is liable to trigger reduced insulin sensitivity." (PMID 25995732, 2015). "The fetal insulin hypothesis is based on the studies, which proves that impairments in fetal insulin secretion or sensitivity caused by genetic factors, such as, e.g., glutamate decarboxylase 2 gene overexpression, are associated with both: low birth weight and early onset obesity." (PMID 24633695, 2015). "Fat-1 mice were also protected from obesity related inflammatory activity and decrements in insulin sensitivity." (PMID 26610527, 2015). "Inhibition of the let-7 family prevents impaired glucose tolerance in mice with diet-induced obesity, partially by improving insulin sensitivity in the liver and muscle." (PMID 25333294, 2015). "In obese rodent models and humans with NAFLD or obesity, a strong inverse correlation has been observed between serum TNFα levels and insulin-stimulated glucose metabolism." (PMID 26077338, 2015). "The Ins1 deficient mice were protected from diet induced weight gain, suggesting that pancreatic hyper-secretion of insulin is required for diet-induced obesity." (PMID 26225266, 2015).
Obesity (continued). "Neonatal insulin treatment induces morphological alterations in hypothalamic structures that leads to the development of obesity and adult hyperinsulinemia in rats." (PMID 26561832, 2015). "Research in animals clearly indicated that insulin from the blood enters the brain via a saturable receptor-mediated transport, and obesity was shown to decrease transport of insulin into the cerebrospinal fluid (CSF) in rats, while data in humans are rare." (PMID 25965336, 2015). "Most studies examining the roles of CORT, insulin and leptin in obesity and behavior have used adrenalectomized rats, which require complicated surgery." (PMID 25754523, 2015). "Association tests and mouse experiments have indicated that CNTN4 is an obesity–insulin targeted gene." (PMID 25898945, 2015). "MCP1 codes for a cytokine with adipogenic functions and mRNA levels are positively correlated with obesity and insulin de-regulation." (PMID 25879645, 2015). "Reaven (1988) observed that insulin-resistant subjects often manifest obesity, high level of low-density lipoprotein (LDL)-cholesterol, low level of high-density lipoprotein (HDL)-cholesterol, fasting hyperglycemia and increased arterial blood pressure." (PMID 26379553, 2015). "All of these features indicate that our HFD animals are compatible with a model of obesity with normal glycaemia and increased plasma insulin levels." (PMID 26108563, 2015). "As described within the methods, we chose from the outset to examine the correlation between markers of obesity and insulin and glucose homeostasis and ECs preoperatively and postoperatively." (PMID 25874237, 2015). "Next, we correlated the gene expression levels of TLR-3 in subcutaneous adipose tissue samples from 80 healthy donors, with markers of obesity, inflammation and insulin sensitivity." (PMID 25867514, 2015). "The chronic nature of obesity produces a tonic low-grade activation of TLR4 that impairs insulin action over time." (PMID 26196892, 2015). "The aim of the present study was to investigate the role of TRPM5 gene ablation on body weight, insulin sensitivity and other metabolic parameters in long-term high caloric diet induced obesity." (PMID 26397098, 2015). "A consistent observation made by our lab and others is that fasting and postprandial ATBF is decreased in obese insulin resistant versus lean insulin sensitive subjects, indicating that oxygen delivery to adipose tissue is indeed impaired in obesity." (PMID 25964776, 2015). "Thiazolidinediones (TZDs), which are known to activate PPAR-γ, are able to improve insulin signaling and glucose uptake by adipose tissue, despite also resulting in side effects, such as obesity." (PMID 25621503, 2015). "Young rats that received the cafeteria diet for 8 weeks developed metabolic syndrome along with obesity, higher hepatic weight, increased plasma levels of glucose, insulin and triglycerides, and insulin resistance." (PMID 26064924, 2015). "The insulin-resistant obesity group had significantly higher levels of BMI, WC, insulin, and systolic blood pressure in adulthood than the insulin-sensitive obesity group, adjusting for race, gender, childhood age and follow-up years." (PMID 26640243, 2015). "Pc1N222D/N222D mice exhibit abnormal proinsulin processing, multiple endocrinological defects, hyperphagia and obesity, while heterozygous mice exhibit an intermediate phenotype for weight gain and fasting insulin processing (Lloyd, Bohan & Gekakis, 2006)." (PMID 25825681, 2015). "Enhanced visceral fatness and several unique features of avian metabolism (i.e., fasting hyperglycemia and insulin insensitivity) mimic overt symptoms of obesity and related metabolic disorders in humans." (PMID 26445145, 2015). "Further researches to establish more appropriate cut-off value of WHR for health risks of obesity and the sexual dimorphism in body fat distribution on insulin resistance in adolescents are necessary." (PMID 26257779, 2015).
Obesity (continued). "The novel adipokine chemerin has been related to insulin-resistant states such as obesity and non alcoholic fatty liver disease (NAFLD)." (PMID 25933030, 2015). "In adipocytes, EPO has been found to decrease preadipocyte differentiation, and mice with adipocyte-specific deletion of EPOR exhibited obesity and decreased glucose tolerance and insulin sensitivity." (PMID 26459940, 2015). "In summary, female C57BL/6J mice were successfully induced to obesity and decreased insulin sensitivity by HFD for 22 weeks." (PMID 25747866, 2015). "In conclusion, transgenic overexpression of Bcl-2 protects islets from cell death caused by obesogenic conditions and improves glucose-induced insulin secretion during obesity." (PMID 26064977, 2015). "Hyperinsulinemic-euglycemic clamp was performed to evaluate insulin sensitivity, which was independently correlated with obesity." (PMID 25747866, 2015). "Mice lacking MC4R had the elevated insulin level and the decreased insulin sensitivity even before manifestation of hyperphagia and obesity." (PMID 28031898, 2015). "In mice fed a high-calorie diet, resveratrol and STACs protect against obesity, increase insulin sensitivity, increase mitochondrial function, and prevent liver steatosis." (PMID 25902704, 2015). "Water soluble cinnamon extract has been shown to increase insulin sensitivity and modulate macrophage activation, a desirable trait for the management of obesity or atherosclerosis." (PMID 24602512, 2014). "The mitogenic and anti-apoptotic environment caused by elevated levels of insulin and IGF-1 in obesity accelerates the stepwise accumulation of mutations and, hence, favor carcinogenesis." (PMID 24829560, 2014). "Recently, we have shown that hNAG-1 transgenic mice are resistant to both genetic and dietary-induced obesity, and have improved insulin sensitivity and higher oxidative metabolism compared to wild-type controls." (PMID 25239873, 2014). "Those mice avoid many deleterious side effects of high-fat diet-induced obesity, displaying improved peripheral insulin sensitivity, lower blood glucose and insulin levels." (PMID 24949727, 2014). "It acts predominantly by reversing the effects of obesity on inflammation, certain signal transduction pathways, and insulin/IGF-1." (PMID 25467785, 2014). "Felig and colleagues originally reported that BCAAs and AAAs correlated with obesity and serum insulin." (PMID 24910999, 2014). "The increased secretion and/or insulin action is related to decreased hunger and food intake, helping to reduce obesity." (PMID 24747593, 2014). "As in humans, obesity during pregnancy in mice results in elevated maternal insulin levels and metabolic programming of offspring." (PMID 24744907, 2014). "The cytokine rise correlated with obesity, the Lee index and the glucose and insulin homeostasis results." (PMID 24979131, 2014). "Obesity also results in reduced insulin sensitivity and altered signal transduction pathways, such as P13Kinase and mammalian target of rapamycin (mTOR), and in mitochondrial metabolism." (PMID 25467785, 2014). "Insulin levels, HOMA-IR and NEFA measurements are the markers we used to determine the association between obesity and the role of the inflammatory process." (PMID 25493077, 2014). "Potential mechanisms by which obesity affects renal physiology include altered renal hemodynamics, insulin resistance, hyperlipidemia, inflammation, oxidative stress and activation of the renin angiotensin-aldosterone system." (PMID 25025298, 2014). "Excessive production of IL-6, as an adipokine, in obesity and diabetes, has an adverse effect on glucose metabolism and insulin sensitivity." (PMID 24563869, 2014). "It appears likely that sensitivity to insulin in obesity is preserved in some tissues where it plays a central role in the GH-IGF axis response, by inhibiting pituitary GH, increasing hepatic GH responsiveness and suppressing hepatic IGFBP-1 secretion." (PMID 26237614, 2014).